IL10 (interleukin 10)
Diseases named in the same sentence as IL10 in open-access papers (continued):
Sharing a sentence is not in itself a finding about the gene and the disease.
campylobacteriosis (continued). "In this study, we therefore investigated the triangle crosstalk (“Ménage à trois”) between the pathogen C. coli, the vertebrate host immunity, and, as third component, the human gut microbiota, applying the clinical campylobacteriosis model using secondary abiotic IL10-/- mice." (PMID 32443576, 2020). "Therefore, these scientifically confirmed health-beneficial effects prompted us to evaluate urolithin-A as a potential novel treatment option for acute campylobacteriosis in C. jejuni infected microbiota-depleted IL-10−/− mice." (PMID 33374868, 2020). "Finally, in separate in vivo experiments, one reversibly non-motile isolate from a stock culture of C. jejuni 11168 was found to be impaired in colonization in the C57BL/6 IL-10–/– mouse model of campylobacteriosis." (PMID 33240235, 2020). "For instance, in IL-10−/− mice that had been pre-treated with antibiotics for 1 week, Nod2 was shown to be essential for controlling campylobacteriosis, given that Nod2−/− IL-10−/− mice exhibited an exacerbation of C. jejuni induced large intestinal inflammation." (PMID 28592996, 2017). "Furthermore, gnotobiotic IL-10-/- mice developed infection-induced immunopathological key features of human campylobacteriosis within six days following peroral C. jejuni infection." (PMID 26406497, 2015). "In a recent study, we were able to show that an oral challenge of secondary abiotic IL-10−/− mice with carvacrol in a prophylactic regimen starting four days prior C. jejuni infection resulted in lowered intestinal pathogen loads and alleviated symptoms of acute campylobacteriosis." (PMID 36830689, 2023). "Hence, the depletion of the gut microbiota in antibiotic-pre-treated IL10−/− mice applied here could be one of the reasons for the limited anti-inflammatory effects observed upon ellagic acid treatment in acute murine campylobacteriosis." (PMID 37896170, 2023). "Following peroral C. jejuni infection, secondary abiotic IL10-/- mice could not only be stably colonized by the pathogen, but also developed acute enterocolitis, mimicking key symptoms of acute campylobacteriosis, such as wasting and bloody diarrhea, within a week post-infection." (PMID 32443576, 2020). "Additionally, curcumin could effectively ameliorate the campylobacteriosis symptoms including apoptosis, T-cell mediated inflammatory responses and colonic barrier dysfunction, observed in C. jejuni infected IL10−/− mice." (PMID 32231139, 2020). "Therefore, we investigated potential pathogen-lowering and immunomodulatory effects following oral application of synthetic urolithin-A during acute campylobacteriosis applying perorally C. jejuni infected, microbiota-depleted IL-10−/− mice as preclinical inflammation model." (PMID 33374868, 2020). "Furthermore, the secondary abiotic IL-10−/− infection model has been proven suitable not only for detailed investigations of immunological aspects of campylobacteriosis, but also for differential analyses of the roles of distinct C. jejuni virulence factors in induction and progression of disease." (PMID 31131028, 2019). "Among these models, gnotobiotic IL-10−/− mice, in which the intestinal microbiota was depleted by broad-spectrum antibiotic treatment, develop acute enterocolitis within 1 week following oral C. jejuni infection mimicking key features of severe human campylobacteriosis." (PMID 26483849, 2015). "Microbiota-depleted IL-10−/− mice could be stably infected with C. jejuni and developed an acute enterocolitis with bloody inflammatory diarrhea within 1 week post infection and showed symptoms typical for severe campylobacteriosis in immunocompromised human patients." (PMID 40395728, 2025). "Within six days post C. jejuni challenge, secondary abiotic mice lacking the interleukin-10 (IL-10) gene (IL-10-/- mice) suffer from severe campylobacteriosis." (PMID 34209990, 2021).
campylobacteriosis (continued). "Given the lack of LOS resistance due to the absence of IL-10, these mice display C. jejuni induced acute enterocolitis within 1 week post-infection (p.i.)thereby mimicking clinical key features of severe campylobacteriosis." (PMID 31921356, 2020). "IL-10 deficient mice represent a robust model to study the pathogenesis of C. jejuni infection because C. jejuni infection of mice lacking IL-10 results in symptoms and pathology that resemble human campylobacteriosis." (PMID 33488580, 2020). "Given that host innate immune responses are pivotal for combating enteropathogenic infections including campylobacteriosis, we here investigated the impact of Nod2 during C. jejuni infection of secondary abiotic mice lacking IL-10−/−." (PMID 28752081, 2017). "A previous elegant in vivo study revealed that NOD2 is essential for the control of campylobacteriosis in antibiotics-treated mice lacking IL-10." (PMID 28127403, 2017). "Taken together, acute enterocolitis in gnotobiotic IL-10−/− mice following C. jejuni, but not E. coli infection mimicks clinical symptoms of severe human campylobacteriosis and is specifically induced by the pathogen." (PMID 22808254, 2012). "Interestingly, prophylactical pretreatment of hma IL-10−/− mice with carvacrol a week before C. jejuni infection significantly mitigated acute campylobacteriosis without affecting the fecal gut microbiota composition." (PMID 40395728, 2025). "Therefore, we analyzed C. coli-induced campylobacteriosis in secondary abiotic IL-10−/− mice with and without TLR4." (PMID 33261211, 2020). "In our clinical intervention study applying an acute campylobacteriosis in vivo model, therapeutic butyrate treatment via the oral route resulted in reduced intestinal inflammatory sequelae, whereas gastrointestinal C. jejuni loads were not affected in infected microbiota-depleted IL-10−/− mice." (PMID 36296229, 2022).
non-small cell lung carcinoma (45 papers, 2011 to 2025). A group of at least three distinct histological types of lung cancer, including non-small cell squamous cell carcinoma, adenocarcinoma, and large cell carcinoma. "The study also noted a significant association between IL-10 and fatigue in females with non-small cell lung cancer (95% CI: 0.49, OR: 0.25–0.9, p = 0.028), though the specifics of the association were not discussed." (PMID 39372868, 2024). "Interleukin-10 expression in tumor-associated macrophages correlates with disease aggressiveness of non-small cell lung cancer." (PMID 21595995, 2011). "IL-10 is associated with the survival, proliferation, and anti-apoptotic activities of various cancers, such as Burkitt lymphoma, non-Hodgkin’s lymphoma, and non-small cell lung cancer." (PMID 37835437, 2023). "For example, in non-small cell lung carcinoma (NSCLC), a loss of classical HLA class I antigens was found to be associated with an upregulation of HLA-G as well as IL-10 expression." (PMID 35185904, 2022). "The expression of inflammatory markers INFγ, TNF, IL10 and PD-1 in a non-small-cell lung cancer mouse model was influenced by TERT." (PMID 39858033, 2025). "According to findings of other studies, IL-6 produced by TAM promoted the occurrence of hepatic cancer through STAT3 signaling pathway, while IL-10 produced by TAM promoted the occurrence of non-small cell lung cancer through STATI pathway." (PMID 38244580, 2024). "Future research should focus on the role of IL-10 in relation to exhausted CD8+ T cells in non-small cell lung cancer, as well as the key factors influencing this dynamic, to improve the efficacy of lung cancer immunotherapies." (PMID 39726592, 2024). "The cooperation of IL-10 and Tregs (along with IL-35) is suggested to promote T-cell exhaustion in murine and human non-small cell lung cancer." (PMID 37554723, 2023). "In non-small-cell lung cancer, IL-10 derived from M2 macrophages promotes cancer stemness through the JAK1/STAT1/NF-κB/Notch1 pathway." (PMID 36838713, 2023). "In diseases such as human cervical cancer eosinophils induce angiogenesis through expression of IL-4, IL-5, IL-10 IL-13 and IL-8) and in human non-small-cell lung cancer (NSCLC), through of the inhibition of T and NK cell function by IDO." (PMID 35406451, 2022). "For example, studies investigating IL-10 levels in non-small cell lung cancer observed that higher IL-10 expression correlated with better survival." (PMID 23755052, 2013). "Correlations between IL-10 haplotypes and clinical characteristics in 385 non-small cell lung cancer patients." (PMID 22848356, 2012). "Correlations between tumor infiltrating lymphocyte counts and IL-10 haplotype in 87 non-small cell lung cancer patients." (PMID 22848356, 2012). "Multivariate analysis of the influence of IL-10 haplotype determined from IL10 mRNA on overall survival and relapse free survival in non-small cell lung cancer patients." (PMID 22848356, 2012). "Various tumor cells have been shown to produce IL-10, including cells from non-small cell lung cancers, melanomas, gliomas, leukemias, and lymphomas." (PMID 24213115, 2011). "Additionally, in non-small cell lung cancer, IL-10, in conjunction with Tregs and IL-35, is believed to further exacerbate T cell exhaustion, suppressing antitumor responses." (PMID 39726592, 2024). "While increased expression of IL-10 produced by TAMs has been correlated with the progression of certain cancers including non-small cell lung carcinoma, the role of IL-10 in promoting CRC is not fully understood as it displays both protective and inflammatory roles." (PMID 30894857, 2019). "Notably, positive roles for IL-10 in the growth and survival of tumor cells have also been described in non-Hodgkin's lymphoma, Burkitt’s lymphoma and non-small cell lung cancer." (PMID 28910419, 2017).
non-small cell lung carcinoma (continued). "Similarly, elevated serum levels of IL-10 were found in non-small cell lung cancer patients; moreover, IL-10 serum levels were shown to be higher in patients with metastatic disease when compared to those with undisseminated cancer." (PMID 23460834, 2013). "We hypothesized that IL-10 haplotypes categorized by IL-10 promoter polymorphisms at –1082A>G, –819C>T, and –592C>A might influence IL-10 expression and give rise to non-small cell lung cancer (NSCLC) patients with poor outcomes and relapse." (PMID 22848356, 2012). "Our results revealed that TAM with high levels of IL-10 expression may play an important role in the progression of non-small cell lung cancer." (PMID 21595995, 2011). "In non-small-cell lung cancer, CXCR4 inhibitors can reduce the expression of CD73, CD38, and IL-10 on metastasis-initiating cells, thereby rescuing the cytotoxic activity of T cells and preventing TAM polarization, possibly by causing a decrease in adenosine and IL-10 production." (PMID 37834375, 2023). "Interestingly, the absence of IL-10 expression has been associated with poor outcome in stage I non-small cell lung cancer (NSCLC), while in late-stage NSCLC, the presence of IL-10-positive macrophages at the tumor margins can be an indicator of poor prognostic outcome." (PMID 22848356, 2012). "Furthermore, increased IL-10 production has been observed in tumor-infiltrating lymphocytes from patients with aggressive malignancies such as advanced non-small cell lung cancer and in peritoneal monocytes from patients with malignant ascites from advanced ovarian cancer." (PMID 24213115, 2011). "For example, SNORA38B promotes IL-10 secretion in tumor cells, leading to the recruitment of CD4+FOXP3+regulatory T cells and reduced infiltration of CD3+CD8+T cells in the TME of non-small cell lung cancer (NSCLC), thereby promoting tumor progression." (PMID 41019058, 2025). "In non-small cell lung cancer cells (NCI-H1299), downregulation of interleukin-10 (IL-10) expression downregulated STMN1 expression and its phosphorylation at S25 and S63." (PMID 40723207, 2025). "In non-small cell lung cancer (NSCLC), BFD decreased the expressions of IL-10, PD-L1, and CD206 in TAMs induced in vitro by PMA and IL-4." (PMID 36311793, 2022). "Additionally, in non-small cell lung carcinoma (NSCLC), it has been shown that a high expression of IL-10 in tumor cells promotes metastasis via angiogenesis and the inhibition of apoptosis." (PMID 34832887, 2021). "Furthermore, as previously discussed, SNORA38B promotes the secretion of IL-10 by tumor cells, which recruit CD4+FOXP3+ regulatory T cells and reduce CD3+CD8+T cell infiltration in the TME of non-small-cell lung cancer." (PMID 41019058, 2025). "Non-small cell lung cancer (NSCLC) biopsy specimens have high intratumoral concentrations of CXCR2 ligands (CXCL1, CXCL5, and CXCL8) and type 2 cytokines interleukin-4 (IL-4), IL-5, IL-10, and IL-13." (PMID 23665907, 2013). "Another study in murine xenograft models of non-small cell lung cancer (NSCLC) using A549 and H1975 cells showed BFD could inhibit tumor growth and prolong the survival in mice by blocking the crosstalk between TAMs and cancer cells through decreasing IL-10 and PD-L1 in vitro and in vivo." (PMID 32733246, 2020).
renal fibrosis (45 papers, 2015 to 2025). A final common manifestation of a wide variety of chronic kidney diseases characterized by glomerulosclerosis and tubulointerstitial fibrosis. "An IL-10 KO (−/−) unilateral ureteral obstruction (UUO) model developed to study the effect of IL-10 in renal tubulointerstitial fibrosis demonstrated that IL-10 deficiency deteriorated tubular injuries and promoted renal fibrosis." (PMID 36552226, 2022). "It was reported that interleukin 10 (IL-10)-deficiency aggravates intestinal and renal fibrosis." (PMID 35198577, 2022). "Interestingly, the expression pro-inflammatory IL-6 was increased in IL-10 deficient mice, suggesting a crucial role for IL-10-induced IL-6 in the protection from renal fibrosis." (PMID 30315190, 2018). "In contrast, exposure of intrinsic renal macrophages to apoptotic cells may promote an anti-inflammatory M2 phenotype associated with release of IL-10 and TGFβ and promotion of tubular repair; prolonged exposure to M2 macrophages may however result in renal fibrosis." (PMID 31134047, 2019). "In an animal model of chronic kidney disease (CKD), treatment with IL-10, delivered as a hydrogel, attenuates macrophage infiltration, apoptosis, and renal fibrosis." (PMID 40535418, 2025). "In a mouse model of unilateral ureteral obstruction, IL-10 inhibits inflammatory factor expression and ameliorates renal fibrosis by antagonizing the TGF-β/Smad3 and NF-κB signaling pathways." (PMID 40092979, 2025). "In the complex environment of ADR‐induced mice, TGF‐β and IL‐10 are released by adoptively transferred MDSCs, activating fibrotic signalling pathways and promoting renal fibrosis." (PMID 38676361, 2024). "For instance, knock-out of the IL-10 in a UUO mice model led to increased renal fibrosis and collagen expression." (PMID 39234562, 2024). "In our previous work, we demonstrated that local subcapsular delivery of either HA hydrogel alone, HA containing IL-10, or IL-10 in saline improved markers of renal fibrosis after AKI." (PMID 37443806, 2023). "Folate-deficient diets further elevated serum TC, LDL-cholesterol, IL-6, tumor necrosis factor (TNF)-α, MCP-1, TGF-β1, and leptin, but decreased IL-10 level, and thus exacerbated renal fibrosis." (PMID 37630806, 2023). "The results showed that AMSCs decreased Scr, M1 macrophages, M1/M2 macrophages, TNF-α, IL-6, IL-1β, and renal fibrosis and increased IL-10 and the number of M2 macrophages." (PMID 34112221, 2021). "In a model of unilateral ureteral obstruction, IL-10 knockout mice demonstrated enhanced renal fibrosis, inflammation, and severe tubular injury." (PMID 32961903, 2020). "Administration of IL-10, coincidently, can suppress renal fibrosis in rats subjected to 5/6 nephrectomy." (PMID 32363192, 2020). "Recently, a connection between IL-10 and inflammatory chemokines has been suggested in renal fibrosis and nerve injury." (PMID 31194740, 2019). "In the late stage of disease, MΦ undergo a switch to an anti-inflammatory macrophage (M2), which can suppress renal inflammation by secreting IL-10, leading to reduced renal fibrosis." (PMID 28416741, 2017). "Consistent with previous studies, relaxin can promote the acquisition of an immunosuppressive M2 phenotype in macrophages; M2 macrophages suppress kidney inflammation by releasing anti-inflammatory mediators, such as IL-10, thus inhibiting renal fibrosis." (PMID 28416741, 2017). "Restoration of renal glutathione levels via administration of NAC led to attenuation of renal fibrosis, augmented expression of anti-inflammatory cytokine IL-10, inhibition of PAI-1 expression and preservation of renal function in experimental DCM." (PMID 29255249, 2017). "M2 macrophages play an anti-inflammatory role, suppressing renal inflammation by releasing anti-inflammatory mediators, such as interleukin (IL)-10, resulting in reduced renal fibrosis." (PMID 28416741, 2017).